CLDN6 (claudin 6)
Diseases named in the same sentence as CLDN6 in open-access papers (continued):
Sharing a sentence is not in itself a finding about the gene and the disease.
ovarian carcinoma (continued). "By performing a differential gene expression analysis using mRNA-seq datasets, PRAME, CTCFL and CLDN6 were selected as strictly tumor-specific TAAs, with high expression in ovarian cancer and at least 20-fold lower expression in all healthy tissues of risk." (PMID 37026005, 2023). "In this study, we describe the selection of PRAME, CTCFL and CLDN6 as strictly tumor-specific targets for patients with ovarian cancer." (PMID 37026005, 2023). "Here, a phase 1 trial is currently recruiting to test this CLDN6-ADC (DS-9606a) for the treatment of advanced ovarian cancer and GCT (NCT05394675)." (PMID 36991316, 2023). "We confirmed this assumption by testing cytotoxicity against the human SK-OV-3 ovarian cancer cell line, which expresses CLDN6 endogenously at extremely low levels." (PMID 36923303, 2022). "Prognostic analysis showed that the overexpression of CLDN6 was related to a poor prognosis for patients with ovarian cancer." (PMID 34249076, 2021). "Claudin 6 (CLDN6) is an oncofetal tight junction protein which is frequently expressed on various human solid cancers such as ovarian cancer cells." (PMID 34838059, 2021). "In the context of emerging CLDN6-targeted therapies, routine assessment of CLDN6 expression may facilitate the development of biomarker-driven therapeutic strategies for advanced ovarian cancer." (PMID 42072801, 2026). "The study continues in patients with CLDN6+ ovarian cancer and non-small cell lung cancer (NSCLC)." (PMID 40722601, 2025). "Furthermore, CLDN6 targeted CAR-NK cells successfully eliminated ovarian cancer cells in subcutaneous and intraperitoneal tumor models." (PMID 39990669, 2025). "Similarly, CTIM-76 is undergoing phase I/II investigation in patients with platinum-resistant ovarian cancer and other CLDN6-positive advanced solid tumors, including endometrial cancer (NCT06515613)." (PMID 41211166, 2025). "Notably, the ORR in patients treated with 0.2–3.0 mg/kg doses of ixotatug vedotin was 33% (21/64), and the ORRs in CLDN6-positive platinum-resistant ovarian cancer patients with 2.4 or 3.0 mg/kg ixotatug vedotin were 50% and 42%, respectively." (PMID 41164107, 2025). "In ovarian cancer, CLDN6 is highly expressed and actively promotes tumor cell proliferation." (PMID 39915118, 2025). "However, the feasibility of using anti-CLDN6 CAR-NK cells to treat ovarian cancer remains to be explored." (PMID 38481806, 2024). "Therefore, our study revealed that CAR-NK cells targeting CLDN6 can induce the expression of PD-L1 on the surface of tumor cells by secreting IFN-γ in the process of killing CLDN6-positive ovarian cancer cells." (PMID 38481806, 2024). "Claudin-6 (CLDN6) has been reported to be overexpressed in ovarian cancer and may be an attractive target for CAR-NK cells immunotherapy." (PMID 38481806, 2024). "By combining mRNA-seq datasets of healthy and tumor tissues, we selected preferentially expressed antigen of melanoma (PRAME), CCCTC-binding factor (CTCFL), and Claudin-6 (CLDN6) as TAAs with high expression in ovarian cancer and at least 20-fold lower expression in all healthy tissues of risk." (PMID 37026005, 2023). "A study revealed that CLDN6 may be a novel targeted therapy for ovarian cancer as a receptor for clostridium perfringens enterotoxin." (PMID 34249076, 2021). "Previous studies and our analyses suggest that CLDN6 may be involved in immune evasion and that they could be an ideal candidate for immunotherapy in ovarian cancer." (PMID 34249076, 2021). "Some of these markers could represent treatment opportunities, such as the embryonic cell junction protein Claudin-6 (CLDN6), against which monoclonal antibodies were recently part of a clinical trial in ovarian cancers (NCT02054351)." (PMID 32575483, 2020). "We speculated that aberrant expression of claudin-6 protein may play a key role in the invasion and metastasis of ovarian cancer and other cancers." (PMID 24245968, 2013).
ovarian carcinoma (continued). "We speculate that up-regulation of claudin-6 may have the same mechanism play a role in occurrence, invasion and metastasis of ovarian cancer." (PMID 24245968, 2013). "Importantly, our group has recently found that claudin-6 can be expressed in ovarian cancer and may represent a novel functional receptor for CPE." (PMID 23685873, 2013). "More broadly, the oncofetal claudins CLDN6 and CLDN9 (normally silenced in adult tissues) are aberrantly activated in ovarian cancers." (PMID 40687428, 2025). "High expression of CLDN6 has been identified as an independent predictor of poor overall survival and PFS in ovarian cancer." (PMID 41465326, 2025). "In fact, one study identified CLDN6 and CLDN9 as additional CPE receptors in ovarian cancer cell lines." (PMID 40687428, 2025). "Therefore, CLDN6 may be an ideal target for CAR-NK cell therapy in ovarian cancer." (PMID 38481806, 2024). "Currently, one Phase I trial has been completed in ovarian cancer with results to be released and there are two trials currently recruiting to explore targeting CLDN6 via ADC in CLDN6 positive advanced solid tumors." (PMID 38371623, 2024). "Preclinically, T cells targeting MSLN, CCNA1, CLDN6, and several MAGE-A family members have been investigated for ovarian cancer as well." (PMID 37026005, 2023). "CLDN6 and CLDN10 were identified as potential prognostic biomarkers and were correlated with immune cell infiltration in ovarian cancer." (PMID 34249076, 2021). "Our study showed that CLDN6 and CLDN10 were prognostic biomarkers correlated with the immune microenvironment in ovarian cancer." (PMID 34249076, 2021). "Our results revealed new roles for CLDN6 and CLDN10 in ovarian cancer and their potential as therapeutic targets in cancer treatment." (PMID 34249076, 2021). "Eight genes were overexpressed in ovarian cancer samples compared with normal tissue samples and included CLDN1, CLDN3, CLDN4, CLDN6, CLDN7, CLDN9, CLDN10, and CLDN16." (PMID 34249076, 2021). "The expression levels of CLDN6 and CLDN10 were also negatively correlated and positively correlated, respectively, with various gene markers of immune cells in ovarian cancer." (PMID 34249076, 2021). "Among them, CLDN3, CLDN4, CLDN6, CLDN10, CLDN15, and CLDN16 were significantly correlated with overall survival in patients with ovarian cancer." (PMID 34249076, 2021). "This study revealed that the prognostic potential of CLDN6 and CLDN10 is related to the tumor immune microenvironment in ovarian cancer." (PMID 34249076, 2021). "Claudin-6 and MMP-2 can be used as important indicators for the judgment of malignant behavior of ovarian cancer such as invasion and metastasis." (PMID 24245968, 2013). "Expression of claudin-6, occludin, and MMP2 was detected in samples of human ovarian cancer tissues by immunohistochemistry and correlated with the clinical properties of the tumors." (PMID 24245968, 2013). "Correlation between the expression of claudin-6, occludin and MMP-2 was evaluated in ovarian carcinoma specimens by McNemar test." (PMID 24245968, 2013). "Consistent with previous reports, both CLDN6 and CLDN10 showed high expression in ovarian cancer." (PMID 34249076, 2021). "Furthermore, CLDN6 and CLDN10 were negatively correlated and positively correlated, respectively, with immune cell infiltration in ovarian cancer." (PMID 34249076, 2021). "While MMP15 was still significantly overexpressed in ovarian cancer biopsies, CLDN6 did not meet these criteria in a bigger cohort." (PMID 31336942, 2019). "The expression of claudin-6 and occludin in ovarian cancer was not correlated with patient age, pathological grade, clinical stage, and metastasis (P > 0.05)." (PMID 24245968, 2013). "Similarly, studies concerning the correlation of claudin-6, occludin and MMP-2 with ovarian cancer have rarely been reported." (PMID 24245968, 2013).
ovarian carcinoma (continued). "However, the feasibility and efficacy of third-generation CAR-NK cells targeting CLDN6 in the treatment of ovarian cancer has not been evaluated." (PMID 38481806, 2024). "Thus, CLDN6 and CLDN10 may participate in immune cell infiltration in ovarian cancer, and these mechanisms may be the reason for poor prognosis." (PMID 34249076, 2021). "Claudin-6 and MMP-2 may play a positive role in the invasion and metastasis of ovarian cancer." (PMID 24245968, 2013). "Our present study shows that claudin-6 and MMP-2 were both up-regulated in ovarian cancer, MMP-2 expression was enhanced with increased clinical stage and metastasis indicates that claudin-6 and MMP-2 may play an important role in the progression of ovarian cancer." (PMID 24245968, 2013). "Consistent with this view, UCI-101, an ovarian cancer cell line highly sensitive to CPE, does not express claudin-3/4 and knockdown of claudin-6 in these cells decreases CPE sensitivity." (PMID 23685873, 2013). "There were no apparent correlations between expression of claudin-6, occludin and MMP-2 in ovarian cancer tissue (P > 0.05)." (PMID 24245968, 2013). "Our correlation studies showed that expression of the TJ proteins claudin-6, occludin and MMP-2 were not correlated in ovarian cancer." (PMID 24245968, 2013).
endometrial cancer (20 papers, 2020 to 2026). Primary or metastatic malignant neoplasm involving the endometrium (mucous membrane that lines the endometrial cavity). "Using this specific mAb, we show that the high CLDN6 expression in endometrial cancer is significantly associated with several clinicopathological factors." (PMID 32987797, 2020). "The conclusion from that study was that aberrant CLDN9 expression is a powerful indicator of poor prognosis in endometrial cancer and could be used alongside CLDN6 to identify high-risk patients." (PMID 40687428, 2025). "In the realm of prognosis, high CLDN2 in colorectal cancer, high CLDN6/9 in endometrial cancer, or low CLDN7 in various cancers could inform risk stratification and follow-up intensity." (PMID 40687428, 2025). "Normally silent in adult endometrium, CLDN6 was found to be highly expressed in a subset of endometrial carcinomas, and high CLDN6 significantly associated with advanced FIGO stage (III/IV), lymph vascular invasion, positive lymph nodes, and distant metastasis." (PMID 40687428, 2025). "CLDN6-high tumors tend to be aggressive, and CLDN6 was identified as an independent prognostic factor for reduced overall and disease-specific survival in endometrial cancer." (PMID 40687428, 2025). "In vitro silencing of CLDN6 in HEC-1-B endometrial cancer cells significantly reduced proliferation, migration, and invasion, accompanied by downregulation of the PI3K/AKT/mTOR pathway." (PMID 41211166, 2025). "We previously reported that abnormal CLDN6/SFK signaling accelerates malignant phenotypes of endometrial cancer cells via hijacking the CLDN6–ERα axis." (PMID 37443730, 2023). "We have recently reported that the EC2 domain and Y196/200 of CLDN6 are required to recruit and activate SFKs and to stimulate malignant phenotypes of endometrial cancer cells." (PMID 37059993, 2023). "We have recently demonstrated that aberrant CLDN6 signaling accelerates endometrial cancer progression in vitro and in vivo by hijacking the CLDN6–ERα axis." (PMID 37059993, 2023). "CLDN6 knockdown significantly inhibited endometrial cancer cell proliferation via the PI3K/Akt/mTOR signaling pathway." (PMID 36362009, 2022). "In endometrial cancer, high CLDN6 expression is an independent prognostic marker for a poor OS of patients." (PMID 34948213, 2021). "We also found that aberrant CLDN6–ERα signaling contributes not only to cellular proliferation, but also to collective cell migration in the leading front of endometrial cancer cells." (PMID 33917356, 2021). "Knockdown of CLDN6 significantly inhibited HEC-1B endometrial cancer cell proliferation via PI3K/Akt/mTOR signaling pathway." (PMID 34948213, 2021). "In a subsequent study, we uncovered that aberrant CLDN6 expression promotes endometrial cancer progression by hijacking the CLDN6–ERα axis." (PMID 33917356, 2021). "The EC2 domain and Y196/200 of CLDN6 were required to recruit and activate SFKs and to stimulate malignant phenotypes of endometrial cancer cells." (PMID 33906582, 2021). "We previously reported that high CLDN6 expression in endometrial cancer is an independent prognostic factor that is significantly associated with several clinicopathological variables." (PMID 33917356, 2021). "We also demonstrate that aberrant CLDN6 expression is an independent prognostic marker for endometrial cancer." (PMID 32987797, 2020). "Analysis of a larger number of cases would be required to draw more solid conclusions about the clinicopathological relevance of the high CLDN6 expression in endometrial cancer subjects." (PMID 32987797, 2020). "Among the analyzed variables, stages III/IV (hazard ratio (HR) 10.93, p = 0.002), distant metastasis (HR 4.68, p = 0.006) and high CLDN6 expression (HR 3.50, p = 0.014) were independent prognostic variables for overall survival of endometrial cancer patients." (PMID 32987797, 2020).
endometrial cancer (continued). "Using immunohistochemistry, we next evaluated the expression of CLDN6 in endometrial cancer tissues resected from 173 patients." (PMID 32987797, 2020). "Association between CLDN6 expression and PI3K/AKT activity in the endometrial cancer cell line HEC-1B is also reported, although the underlying molecular basis is not defined." (PMID 32987797, 2020). "CLDN6 was primarily distributed along the cell membranes of endometrial carcinoma cells, and the signal intensity (SI) appeared to vary among endometrial cancer subjects." (PMID 32987797, 2020). "In the present study, we generated a highly specific anti-human CLDN6 monoclonal antibody, and assessed the prognostic significance of aberrant CLDN6 expression in endometrial cancer tissues." (PMID 32987797, 2020). "Our immunohistochemical study revealed intratumoral heterogeneity of CLDN6 expression within human endometrial cancer tissues." (PMID 32987797, 2020). "We also demonstrated that aberrant CLDN6 expression is an independent prognostic variable for endometrial cancer." (PMID 32987797, 2020). "This study indicates that high CLDN6 expression in endometrial cancer relates to several clinicopathological factors and is an independent prognostic factor." (PMID 32987797, 2020). "By immunohistochemical staining and semi-quantification, we evaluated the relationship between CLDN6 expression and clinicopathological parameters in tissues from 173 cases of endometrial cancer." (PMID 32987797, 2020). "CLDN6 is another oncofetal protein aberrantly expressed in endometrial cancer." (PMID 40687428, 2025). "In summary, claudin dysregulation in endometrial cancer is tied to subtype, invasion, and outcome: high CLDN6/CLDN9 confers poor survival, and may also reflect an immune-cold microenvironment analogous to ovarian tumors." (PMID 40687428, 2025). "In addition to the bsAbs already discussed, other promising candidates in endometrial cancer include those targeting CLDN6." (PMID 41211166, 2025). "However, a previous study has demonstrated significant correlations between CLDN6 expression, molecular subtypes, and clinical characteristics in various adult cancers, particularly in endometrial carcinoma, using transcriptomic data." (PMID 40149257, 2025). "Taken together, we hypothesized that the CLDN4 signaling might regulate breast cancer progression by regulating the nuclear receptor activity in a similar mechanism to CLDN6 in endometrial cancer." (PMID 37059993, 2023). "Additionally, we reported that aberrant CLDN6/SFK signaling promotes endometrial cancer progression in vitro and in vivo by hijacking the CLDN6–ERα axis." (PMID 37443730, 2023). "Moreover, we characterized the human endometrial carcinoma cell line Ishikawa expressing CLDN6, further confirming that pSFK is concentrated to cell boundaries together with CLDN6." (PMID 37443730, 2023). "However, we have recently reported that aberrant CLDN6 signaling advances endometrial cancer progression via hijacking of the CLDN6–ERα pathway." (PMID 33917356, 2021). "Furthermore, the high CLDN6 expression was an independent prognostic marker for overall survival of endometrial cancer patients (hazard ratio 3.50, p = 0.014)." (PMID 32987797, 2020). "High CLDN6 expression in endometrial cancer is a biomarker to predict poor prognosis." (PMID 32987797, 2020). "Thus, aberrant CLDN6 expression appeared to correlate with poor outcome in patients with endometrial cancer." (PMID 32987797, 2020). "Taken together with the notion that ERα acts as a master transcription factor in endometrial cancers, aberrant CLDN6 signaling may promote the malignant behavior of endometrial cancer cells via hijacking the CLDN6–ERα pathway." (PMID 32987797, 2020). "CLDN6 is also highly expressed in germ cell tumors, including seminomas, embryonal carcinomas and yolk sac tumors, as well as in some cases of gastric adenocarcinoma, lung adenocarcinoma, ovarian adenocarcinoma and endometrial carcinoma." (PMID 32987797, 2020).
endometrial cancer (continued). "It is unknown how the high CLDN6 expression leads to poor prognosis in endometrial cancer subjects." (PMID 32987797, 2020). "Though, a current study describing the generation and preclinical characterization of a CLDN6-ADC for the treatment of ovarian and endometrial cancer using a patient-derived xenograft model showed reduced tumor volume specifically in CLDN6+ tumors." (PMID 36991316, 2023). "Therefore, CLDN6 may be a promising therapeutic target for endometrial cancer." (PMID 32987797, 2020). "Claudin-6 and claudin-4, which are absent in normal adult samples, are aberrantly expressed in endometrial cancer." (PMID 36091010, 2022). "These tumors were composed of CLDN6-positive and -negative subpopulations, even in endometrial cancer tissues with high CLDN6 expression." (PMID 32987797, 2020). "The relationship between CLDN6 expression and the Cancer Genome Atlas (TGCA) molecular classification of endometrial cancer may be also considered in future experiments." (PMID 32987797, 2020). "Also, CLDN6 regulates the PI3K/AKT/mTOR signaling pathway in HEC-1B endometrial carcinoma cells and EGFR/AKT/mTOR signaling pathway in HepG2 cells, but the mechanisms of how CLDN6 affects the signaling pathway in both HEC-1B and HepG2 cells remain to be verified." (PMID 34948213, 2021). "Interestingly, CLDN6 exhibited intratumoral heterogeneity, and CLDN6-positive and negative subpopulations were observed in endometrial cancer tissues even in the subjects with high CLDN6 expression." (PMID 32987797, 2020).